MTA2 (metastasis associated 1 family member 2)
Diseases named in the same sentence as MTA2 in open-access papers (continued):
Sharing a sentence is not in itself a finding about the gene and the disease.
tumor (continued). "In human colorectal cancer, previous work revealed that MTA1 and MTA2 expression was up-regulated and correlated to tumor aggressiveness." (PMID 28418887, 2017). "Instead of cell invasion, colony formation in soft agar and tumor growth in vivo were significantly enhanced by MTA2 overexpression, contrast to MTA2 knockdown." (PMID 25929737, 2015). "For example, metastatic tumor antigen 2 (MTA2) is a member of the MTA family and is closely associated with tumor progression and metastasis." (PMID 23825676, 2013). "It has been proven that MTA2 was expressed in many tumor cell lines and was correlated with tumor invasion and metastasis." (PMID 20704817, 2010). "Silencing MTA2 via siRNA could therefore suppress metastatic signaling while restoring tumor-suppressive functions in PDAC." (PMID 40943389, 2025). "Finally, MTA2 depletion significantly reduced tumor metastasis and the formation of lung nodules in vivo." (PMID 39248711, 2024). "Thus, mounting evidence suggests that MTA2 plays a crucial role in tumor progression and affects cancer prognosis." (PMID 39248711, 2024). "Silencing MTA2 using shRNA restored autophagy and inhibited tumor migration and invasion." (PMID 39840028, 2024). "Autophagy plays a complex role in modulating tumor metastasis by influencing EMT, matrix remodeling, and invasion MTA2, a key driver of tumor metastasis, has been shown to suppress autophagy-related protein LC3-II expression in oral cancer cells, facilitating metastasis." (PMID 39840028, 2024). "The results indicated that MTA2 is a promising indicator for prediction of tumor prognosis." (PMID 37371463, 2023). "Additionally, we investigated the role of MTA2 in promoting tumor growth in vivo by constructing a subcutaneous xenograft model." (PMID 36741260, 2023). "A xenograft tumor model study also showed that MTA2 knockdown inhibits tumor growth in vivo." (PMID 36741260, 2023). "Our results suggested that MTA2 was differentially expressed in different tumor stages." (PMID 37371463, 2023). "Therefore, we believed that MTA2 plays a prominent role in the tumor immune microenvironment in HCC." (PMID 37371463, 2023). "We found that MTA2 overexpression was correlated with both good and poor tumor prognosis, depending on cancer type, indicating the multifaceted roles of MTA2 in different tumors, which might be related to the diverse tumor microenvironment of various tumors." (PMID 37371463, 2023). "This study can provide insight into the role of MTA2 in tumor immunotherapy." (PMID 37371463, 2023). "The results showed that the downregulation of MTA2 significantly reduced tumor volume and weight." (PMID 36741260, 2023). "This indicated that the effects of MTA2 in diverse tumors were multifaceted, which might be relevant to the tumor microenvironment of different tumors." (PMID 37371463, 2023). "In summary, these data support our overall hypothesis that SMYD3 cooperates with the NuRD (MTA1/MTA2) complex to inhibit expression of a series of tumor suppressor genes, leading to tumor progression." (PMID 36575438, 2022). "To assess whether MTA2 also affected PDAC tumor growth in vivo, we injected the MTA2-depleted MIA Paca-2 cells with stably expressing firefly luciferase into the right flank of immunodeficient nude mice." (PMID 30814496, 2019). "Moreover, high MTA2 expression was markedly correlated with tumour grades and indicated low survival rates in accordance with the clinical pathologic data from our patients and TCGA database." (PMID 31771219, 2019). "As the tumour grade became severe, MTA2 expression was enhanced." (PMID 31771219, 2019). "The different results between cell proliferation assay and in vivo experiments indicated that interactions between tumor cells and its microenvironment could correlate with growth promoting effect of MTA2." (PMID 25929737, 2015).
tumor (continued). "Furthermore, we found that combined inhibition of PI4KIIα and EGFR suppressed both PI3K/AKT and MAPK/ERK pathways, and resulted in downregulation of multiple oncogenes like PRDX2, FASN, MTA2, ultimately leading to suppression of tumor growth." (PMID 24801752, 2014). "Additionally, engineered transcriptional repressors or small-molecule inhibitors might disrupt MTA2’s interaction with chromatin-remodeling complexes, impairing tumor invasiveness." (PMID 41159000, 2025). "Therefore, transcriptional promotion of MCM5 by MTA2 may be a key mechanism in regulating GC tumor growth." (PMID 36741260, 2023). "We speculated that MTA2 might play a crucial role in tumor development." (PMID 37371463, 2023). "Therefore, the transcriptional suppression of PTEN by MTA2 may be a key mechanism in regulating PDAC tumor growth." (PMID 30814496, 2019). "MMP12 expression is regulated positively by MTA2 via AP1 through phosphorylation of the pathway ASK1/MEK3/p38/YB1, leading to tumor cell metastasis." (PMID 41516135, 2025). "The hypomethylated epigenetic signal was enriched for a number of transcription factor binding sites, including MTA2 and MTA3 which have been shown to have relationships to metastasis and tumor growth in multiple cancers." (PMID 41000815, 2025). "To explore how MTA2 plays the tumor-promoting role, we divided TCGA-STAD tumor samples into two groups according to the median expression value of MTA2 for GSEA analysis." (PMID 36741260, 2023). "In our study, we found a higher level of MTA2 in HCC tissues than in normal tissues and a significant correlation between tumor grade and overall survival of HCC patients." (PMID 31777601, 2019). "Using CCK-8, colony formation and transwell assays, and a xenograft tumor model, we revealed that MTA2 promoted PDAC cell proliferation, migration, and invasion in vitro and PDAC tumor growth in vivo by downregulation of PTEN." (PMID 30814496, 2019). "In summary, our data suggested that MTA2 was overexpressed in RCC tissues and cells and positively correlated with tumour grade and MMP-9 expression in vitro and in vivo." (PMID 31771219, 2019). "The growth rate of MTA2 knockdown SGC-7901 xenografts was slower than that in control group (P = 0.043), and the average tumor weight of xenografts was also lower (0.82 ± 0.08 g vs. 2.12 ± 0.58 g, P = 0.021)." (PMID 24010737, 2013). "By immunohistochemical staining, we could confirm some of these gene products like MTA2, ESAM, and LGALS1 in primary tumour and in metastasized cells in the lung of the two clones, but CTTN only in primary tumour sections not in metastatic cells of the lung." (PMID 34693476, 2022). "Apart from MTA2, all other NuRD subunits tested are highly expressed in FP-RMS tumor tissue." (PMID 32744500, 2020). "When MTA2 was silenced, MEQ could no longer upregulate SerRS expression in MDA-MB-231 cells, strongly suggesting that MTA2 was a key mediator of MEQ, which induced SerRS expression and subsequently inhibited tumor angiogenesis." (PMID 32944400, 2020). "Compared with the shSCR group, MTA2 shRNA could increase PTEN levels and decrease p-AKT levels in the isolated tumor samples." (PMID 30814496, 2019). "Therefore, we proposed that the knockdown of MTA2 downregulates the expression of MMP2, inhibiting tumor metastasis in HCC." (PMID 31777601, 2019). "It was determined that MTA2 is an oncogene and a poor prognostic factor for the OS of HCC patients and that changes in p38MAPK-mediated MMP2 expression may contribute to tumor metastasis." (PMID 31777601, 2019). "Thus, we demonstrated that miR-1236-3p functioned as a tumor suppressor in GC at least partly through inhibition of the EMT process and PI3K/Akt signaling pathway by targeting MTA2." (PMID 29743816, 2018). "However, when MTA2/NuRD complex dissociates from the promoter region of NF-κB target genes and IKK2-dependent positive regulation of MTA2 occurs, it leads to the activation of NF-κB signaling and further promotes EMT and tumor metastasis." (PMID 38433280, 2024).
tumor (continued). "Additionally, MTA2 mRNA and protein levels (from the HPA database) were significantly increased in GC tissues relative to non-tumor tissues, suggesting that MTA2 may play a vital role in GC progression." (PMID 36741260, 2023). "MTA2 and MBD3 might co-regulate tumor development through co-expression and physical interaction in the cell membrane, mitochondria, and nucleus, leading to tumor cell expression and migration." (PMID 37371463, 2023). "Interestingly, as a cell cycle pathway member, MCM5 was highly expressed in GC tumor tissue relative to non-tumor tissue and positively correlated with MTA2." (PMID 36741260, 2023). "However, another study demonstrated that MTA2 overexpression enhanced colony formation and tumor growth of GC cells, but was not important in cancer cell migration and metastasis." (PMID 31645899, 2019). "Notably, the MTA1, MTA2 and MTA3 components of the NuRD complex have been shown to play an important role in the ER and HER2 pathways regulating the epithelial-mesenchymal transition (EMT) and tumor cell invasion and metastasis, but they have distinct effects." (PMID 29625565, 2018). "However, unlike MTA1 and MTA2 which were mainly involved in cancer progression and metastasis, MTA3 possesses both tumor-suppressing and tumor-promoting properties depending on specific cancer types." (PMID 31552166, 2019).
cancer (42 papers, 2006 to 2025). A tumor composed of atypical neoplastic, often pleomorphic cells that invade other tissues. "We mainly summarize the evidence supporting the view that MTA2 is one of the most frequently genes amplified than mutated in different types of cancer." (PMID 41159000, 2025). "Several studies suggest that MTA2 is highly expressed in human cancers and is directly associated with malignancy, metastasis, drug resistance, and a poor cancer prognosis." (PMID 39248711, 2024). "To investigate the association between MTA2 and cancer prognosis, we performed a survival analysis of MTA2 based on the “survminer” and “survival” R packages (p < 0.05)." (PMID 37371463, 2023). "The results of this study concluded that the expression of MTA2 was associated with the degree of immune infiltration in a variety of cancers." (PMID 37371463, 2023). "We found that MTA2 was positively associated with Type 2 helper T cells (a subset of CD4+ T cells) in most cancers." (PMID 37371463, 2023). "This indicated that MTA2 has a substantial association with T cells CD4 in pan-cancer and that MTA2 expression plays an indispensable role in the immune function of pan-cancer." (PMID 37371463, 2023). "By analyzing the cBioPortal database, we found that the mutation frequency of MTA2 in pan-cancer was 1.5% (p < 0.05)." (PMID 37371463, 2023). "More importantly, we discovered that MTA2 overexpression was associated with cancer immunity, TMB and MSI." (PMID 37371463, 2023). "Further efforts are necessary to identify alternative means of targeting PRMT5 and MTA2 in MTAP-ve cancers to benefit from the high-MTA environment of MTAP-deficient cancers." (PMID 36913304, 2023). "Metastasis-associated protein 2 (MTA 2) is closely related to the progression of various cancers such as liver cancer, gastric cancer, and colorectal cancer." (PMID 38069041, 2023). "MTA2 is upregulated in human cancers and is associated with an aggressive phenotype, treatment resistance, and a poor prognosis in cancer patients." (PMID 37371463, 2023). "Metastasis-associated protein 2 (MTA2) was previously known as a requirement to maintain malignant potentials in several human cancers." (PMID 31771219, 2019). "We analyzed the point mutations of MTA2 in pan-cancer from the SangerBox online website." (PMID 37371463, 2023). "In addition, DIM inhibited cancer cell invasion by suppression of metastasis-associated protein 2 (MTA2), NF-κB, interleukin 1 receptor-associated kinase 1 (IRAK1), and epidermal growth factor receptor (EGFR) based on upregulation of miR-146a." (PMID 35582221, 2020). "Since MTA2TR is adjacent to MTA2, one of the pivotal metastasis-associated protein in numerous cancers, we firstly presumed that whether MTA2 is a downstream target of MTA2TR to exert promoting effects in PC." (PMID 31410216, 2019). "Moreover, both ETS and SP1 are reported to promote the transcriptional activity of MTA2, which belongs to metastasis associated family and is highly expressed in tumors, resulting in promotion of cancer cell aggressiveness." (PMID 26177288, 2015). "Clinical studies show the higher expression of MTA2 is usually associated with advanced tumors and might be used as a poor predictor in the prognosis of patients, but the mechanism by which it promotes cancer progression is distinguished with these cancers." (PMID 41159000, 2025). "Validate MTA2 synthetic lethality partners using CRISPR-Cas12a multiplex screens across cancer lineages with 3D chromatin architecture defects." (PMID 41159000, 2025). "Considering various studies demonstrating the importance role of MTA2 in normal development and varieties of human cancers." (PMID 41159000, 2025). "This review is critical as it synthesizes scattered evidence, bridging MTA2’s roles in normal processes (embryonic development, immune cell differentiation) and cancer biology." (PMID 41159000, 2025).
cancer (continued). "Many studies used TCGA data to explore MTA2 genes in cancers, however, TCGA exhibits inherent technical and biological biases." (PMID 41159000, 2025). "In general, our study reveals an essential role of the circMTA2/UCHL3/MTA2 axis in GC progression, expanding the current knowledge on the molecular mechanism of MTA2-mediated cancer progress." (PMID 38474064, 2024). "In conclusion, we identified a cancer-promoting axis (circMTA2/UCHL3/MTA2) in GC progression, which paves the way for us to design and synthesize targeted inhibitors as well as combination therapies." (PMID 38474064, 2024). "MTA2 mainly acts as a transcription factor that has been amplified in many types of cancers, including GC." (PMID 38474064, 2024). "Other studies have shown that MTA2 is overexpressed in a variety of cancers, including cervical, liver, breast, and lung." (PMID 39248711, 2024). "According to the “EPIC”, “MCPcounter”, “GSVA”, and “estimate” R packages, we performed an immunoassay for MTA2 in pan-cancer." (PMID 37371463, 2023). "By OS analysis, we found that the prognosis of MTA2 in LIHC was the most significant in 33 cancer types (p < 0.001), and the results indicated that high expression of MTA2 in LIHC had a poor prognosis." (PMID 37371463, 2023). "The results suggested a strong interaction of MTA2 with stimulatory and inhibitory immune genes in most cancers." (PMID 37371463, 2023). "Based on the “fmsb” R package, we applied Spearman’s correlation coefficient to analyze the correlation of MTA2 with MSI in pan-cancer." (PMID 37371463, 2023). "To assess the accuracy of the model for MTA2 in tumors, we plotted radar plots showing the AUC of MTA2 in pan-cancer." (PMID 37371463, 2023). "In this study, we found that MTA2 was significantly enriched in antigen processing and presentation, cancer, T-cell receptor signaling, and the regulation of autophagy pathways in cancer via enrichment analysis." (PMID 37371463, 2023). "According to the “fmsb” R package, we also applied Spearman’s correlation coefficient method to analyze the correlation of MTA2 expression in pan-cancer with TMB." (PMID 37371463, 2023). "This was because the SATB1-gene interaction network generated by FunRich software suggested that SATB1 was closely associated with other cancer-correlated genes, such as GATA3, HDAC1, and MTA2." (PMID 34604093, 2021). "A higher MTA2 expression is clearly related to a poorer prognosis in cancer patients and is involved in the development and progression of cancer during carcinogenicity." (PMID 30814496, 2019). "Metastasis-associated protein 2 (MTA2), a 668-amino-acid protein, appears to augment the potential of cancer cells by regulating cytoskeletal organization." (PMID 31777601, 2019). "Patients diagnosed with grade 2 or 3 cancer had a significantly higher percentage of MTA2 expression compared with those diagnosed with grade 1 (p = 0.002)." (PMID 31771219, 2019). "Among the candidates, MTA2, a potent oncogene that is frequently upregulated in human cancers, was predicted to be a miR-1236-3p target by all three of the algorithms and was selected for further experimental verification." (PMID 29743816, 2018). "All family members of metastasis tumor antigen (MTA) proteins including MTA1, MTA2, MTA3 and MTA1s have been closely linked to cancer progression and metastasis." (PMID 23671646, 2013). "Correlating cellular results with mouse conclusion reveal that MTA2 may be an elusive direct target for cancer therapy." (PMID 41159000, 2025). "MTA2 is positively correlated with most immune cells in pan-cancer." (PMID 41159000, 2025). "In the future, to further validate the feasibility of MTA2 as a target for cancer therapy." (PMID 41159000, 2025). "MTA2, a key transcriptional regulator, plays pivotal roles in normal development and cancer, yet its physiological functions and pathogenic mechanisms remain incompletely understood." (PMID 41159000, 2025).